SIRT7 (sirtuin 7)
Diseases named in the same sentence as SIRT7 in open-access papers (continued):
Sharing a sentence is not in itself a finding about the gene and the disease.
tumor (continued). "Higher SIRT7 expression in highly graded breast and PCa tissues correlates with tumor progression and reduced overall patient survival, making SIRT7 a prognostic factor for breast and PCa patients." (PMID 40165597, 2025). "The high expression levels of SIRT7 are consistent with the characteristics of high synthesis and high metabolism observed in tumor cells." (PMID 40165597, 2025). "By regulating succinylation levels on specific substrates, SIRT7 influences oncogenic signaling pathways and contributes to tumor cell survival and proliferation." (PMID 40586636, 2025). "This evidence underscores the potent tumor-suppressive role of SIRT7, likely rooted in its ability to stabilize the genome and counteract oncogenic stress." (PMID 41471367, 2025). "Beyond DNA repair, SIRT7 coordinates broader molecular networks that influence tumor behavior, positioning it as an appealing target for therapeutic intervention." (PMID 41471367, 2025). "Increased expression of SIRT7 has also been described in hepatic, ovarian, breast, and lung cancers, but it appears to be a tumor suppressor in head and neck squamous cell carcinoma." (PMID 40149343, 2025). "Mechanistically, SIRT7 orchestrates tumor progression and immune evasion by selectively activating the UPR." (PMID 41425553, 2025). "Initially, we employed the CCK − 8 and EdU assays to evaluate the effect of decreased SIRT7 expression on the proliferation of tumor cells." (PMID 41114868, 2025). "In contrast, SIRT7 is overexpressed in cervical squamous cell carcinoma and promotes tumor growth through a positive feedback loop with USP39 and FOXM1, which regulates autophagy and oxidative stress." (PMID 41471349, 2025). "Several studies have also confirmed that SIRT7 drives histone deacetylation, and mediates the transcriptional repression of several tumor suppressor genes." (PMID 40301349, 2025). "Therapeutically, SIRT7 or secreted SIRT2 are potential targets for suppressing tumor growth and stimulating immune response." (PMID 41425553, 2025). "A combination of SIRT7 inhibition with anti-PD-1 therapy synergistically enhanced tumor control in vivo, which implied that SIRT7 inhibition enhances checkpoint immunotherapy." (PMID 41425553, 2025). "SIRT7’s tumor versus cardiac muscle dualism highlights the need for highly selective targeting strategies." (PMID 41425553, 2025). "Although DDX3X overexpression significantly promoted PDAC proliferation, the tumor-promoting effects were partly counteracted by SIRT7 suppression in the subcutaneous xenograft model." (PMID 38316768, 2024). "Within this family, SIRT7 emerges as a versatile player in tumorigenesis, displaying both pro-tumorigenic and tumor-suppressive functions in a context-dependent manner." (PMID 38383727, 2024). "Low nuclear levels of SIRT7 correlate with aggressive tumor phenotypes, making it a significant biomarker for disease prognosis." (PMID 39682281, 2024). "In both in vivo and in vitro settings, the attenuation of SIRT7 O-GlcNAcylation at S136 was observed to impede tumor progression, thereby underscoring the significance of this modification in the context of PDAC." (PMID 39682281, 2024). "Ablation of SIRT7 in PCa cells diminishes tumor growth, curbs cell migration, and attenuates the formation of metastases in mouse xenograft models." (PMID 38383727, 2024). "Through the deacetylation of H3K18ac in local promoters, SIRT7 and Elk4 work together to sustain oncogenic transformation and tumor growth." (PMID 39479446, 2024).
tumor (continued). "It is evident that SIRT7 acts to counteract tumor formation in response to carcinogens and oncogenes in vivo, aligning with its crucial function in maintaining genomic stability." (PMID 38383727, 2024). "It is widely acknowledged that O-GlcNAcylation maintains the stability of the SIRT7 protein, which inhibits the transcription of a few tumor suppressor genes." (PMID 38316768, 2024). "In tumor-bearing mice, SH3PXD2A-AS1 inhibition suppressed tumor growth and the protein levels of Ki67, SIRT7, and FOXM1." (PMID 39020302, 2024). "The depletion of SIRT7 in these cells diminishes proliferation, invasion and migration in vitro, and it restricts tumor growth in mouse xenograft models." (PMID 38383727, 2024). "T cell exhaustion, a known mechanism widely described to inhibit CD8+ T cell proliferation and their capability to kill tumor cells, has been linked to several genes highly expressed in various tumor tissues like CEACAM1 and SIRT7." (PMID 39117605, 2024). "It has also been established that SIRT7 mediates the deacetylation of histone H3K18, resulting in the transcriptional repression of tumor suppression-associated genes." (PMID 39719443, 2024). "SIRT7 has emerged as a multifaceted regulator of tumorigenesis, exhibiting duality in its roles as both a pro-tumorigenic and tumor-suppressive entity." (PMID 39682281, 2024). "We found that suppression of SIRT7 significantly reduced tumor growth, whereas inhibition of ARF in transplanted tumor cells reverted this phenotype." (PMID 38870055, 2024). "Within these tumor contexts, SIRT7 heightens the activation of the MAPK signaling cascade, thereby triggering epithelial-to-mesenchymal transition (EMT) and ultimately fostering migratory potential, promoting the formation of metastasis." (PMID 38383727, 2024). "Genetic alterations, such as specific oncogene activation or tumor suppressor inactivation, can significantly modulate the impact of SIRT7 on tumor progression." (PMID 38383727, 2024). "In Sirt7−/−; ApcMin/+ mice, increased Wnt signaling, dysregulated chromosome segregation, and impaired DNA repair drive an early tumor incidence and increase tumor load compared with ApcMin/+ mice." (PMID 37676263, 2024). "Our results for tumor weight and volume suggest that stable DDX3X overexpression promotes tumor growth compared to that in the control group, while SIRT7 knockdown suppressed the tumor growth-promoting effects of DDX3X overexpression on tumor formation." (PMID 38316768, 2024). "SIRT7 promotes the proliferation and invasion of tumor cells by activating related signaling pathways." (PMID 38360598, 2024). "SIRT7, whose expression correlates with aggressive tumor phenotypes and poor outcomes, also holds significant promise in predicting disease prognosis." (PMID 39682281, 2024). "The potential tumor-suppressive role of SIRT7 extends its reach to encompass hematologic malignancies." (PMID 38383727, 2024). "In fibrosarcoma cells, SIRT7 assumes a critical function in sustaining tumor growth through epigenetic repression of pivotal tumor suppressors including RPs via H3K18 deacetylation." (PMID 38383727, 2024). "By using mouse model approach, we also provide evidence that SIRT7 knockdown inhibited the tumor growth." (PMID 37957720, 2023). "Apart from the direct effect on tumor cell survival, SIRT7 up-regulation also repressed anti-tumor immunity by promoting PD-L1 expression via the IRE1α-XBP1 axis." (PMID 36918544, 2023). "We previously developed a specific SIRT7 inhibitor 2800Z, which suppressed tumor growth and enhanced the chemosensitivity of sorafenib." (PMID 36678616, 2023). "As a result, the knockdown of SIRT7 similarly induced prominent delay of tumor growth in C57B6/L mice." (PMID 36918544, 2023).
tumor (continued). "SIRT7 expression in the tumor tissues of CSCC patients (n = 40) and normal adjacent tissues (n = 40) was also measured using qRT-PCR analysis." (PMID 37957720, 2023). "We observed decreased tumor volume after SIRT7 silencing, and the growth rate of mouse tumor was lower after SIRT7 knockdown." (PMID 37957720, 2023). "The knockdown of SIRT7 induced prominent delay of tumor growth, with the tumor weight and tumor volume significantly down-regulated in comparison to the control." (PMID 36918544, 2023). "In summary, our findings demonstrate that SIRT7 is a stress-responsive protective factor and plays an oncogenic role by simultaneously enabling tumor cell survival and immune evasion via the activation of unfolded protein response." (PMID 36918544, 2023). "In conclusion, our key findings from this report demonstrate that SIRT7 facilitates the proliferation, autophagy and tumor growth while inhibits the apoptosis and ROS production in CSCC." (PMID 37957720, 2023). "By measuring the changes in tumor volume over time, we found that the tumor volumes of both SIRT7-knockdown and LAP2α-knockdown groups were increased approximately twice than that of the control group." (PMID 37056924, 2023). "In the future, the therapeutic influence of specific inhibitors on CSCC tumor tissue genesis will be explored by analyzing the effect of USP39-specific acetylation on SIRT7/USP39/FOXM1 positive feedback axis." (PMID 37957720, 2023). "As revealed by the UALCAN analysis, SIRT7 mRNA levels were significantly upregulated in the tumor tissues of CSCC patients relative to normal tissues." (PMID 37957720, 2023). "SIRT7 can promote the secretion of IRE1α-dependent tumor-promoting factors and alter the tumor immune microenvironment, thereby mediating tumorigenesis." (PMID 37795354, 2023). "Nevertheless, the results support that SIRT7 mRNA and plausible protein levels decrease in a Sirt7+/− tumor environment." (PMID 38234684, 2023). "Compared with the mice injected with SIRT7 WT, the mice injected with S136A, WT+shOGT, or S136A+shOGT exhibited decreased tumour volume and mass." (PMID 35422493, 2022). "In terms of KAT5, SIRT4, SIRT6 and SIRT7, these four genes demonstrated higher expression in tumours than in adjacent tissues." (PMID 36308411, 2022). "SIRT7 levels are increased in lung cancer tumor tissues and cell lines, and these levels were also associated with clinicopathologic features, including positive lymph node metastases, high pathologic stage, and large tumor size." (PMID 35585284, 2022). "Tumour weight and volume in the animals injected with NC cells increased significantly compared with those in the mice administered SIRT7-depleted cells." (PMID 35422493, 2022). "Representative images indicated that expression of SIRT7 in tumour tissues was higher than that in matched peritumour tissues." (PMID 35422493, 2022). "Adding miR-138-5p inhibitor or overexpression of SIRT7 partially reversed the DNA damage phenotype caused by circ-ZNF609 depletion, and circ-ZNF609 depletion reduced the tumor size, tumor volume, and tumor weight through the miR-138-5p/SIRT7 axis in vivo." (PMID 35938040, 2022). "SIRT7 was overexpressed in glioblastoma multiforme tumors compared to matched adjacent non-tumor tissues and mainly in those of high grade." (PMID 35585284, 2022).
tumor (continued). "In vivo and in vitro experiments showed that blocking SIRT7 O-GlcNAcylation at S136 attenuates tumour progression." (PMID 35422493, 2022). "Overall, these results indicate that targeting SIRT7 has great potential to substantially enhance the anti-tumor efficacy of combined chemotherapy and IF." (PMID 34433808, 2021). "SIRT7 underpins the anti-tumor effect of intermittent fasting (IF) by enhancing the effects of fasting on GSK3β activity and AMPK signaling." (PMID 34433808, 2021). "SIRT7 hyperphosphorylation achieves anti-tumor activity by disrupting the SKP2-SCF E3 ligase, thus preventing SKP2-mediated K63-linked AKT polyubiquitination and subsequent activation." (PMID 34433808, 2021). "In accordance with the hyperactivation of the oncogenic EGF/Ras signaling pathway and the rapid tumor progression, Vegfa and Hif1α expression was significantly upregulated in PyMT;Sirt7+/− tumors." (PMID 34433808, 2021). "Given that SIRT7-modulated AKT activity, we investigated the role of SIRT7 in tumor initiation via oncogenic EGF/AKT signaling." (PMID 34433808, 2021). "Our lead compounds, 2800Z and 40569Z, specifically inhibited the deacetylation activity of SIRT7, blocked proliferation, enhanced chemosensitivity of sorafenib, and reduced tumor burden both in vitro and in vivo." (PMID 35174171, 2021). "Multiple lines of evidence indicate that inactive SIRT7 suppresses tumor growth, and our data also show that compounds 2800Z and 40569Z specifically inhibit SIRT7 enzyme activity and suppress tumor growth." (PMID 35174171, 2021). "The expression of SIRT1–7 was not correlated with the survival of the patients; however, SIRT3 and SIRT7 expression was significantly correlated with the proliferation marker Ki-67, implying roles in tumor cell proliferation." (PMID 33669567, 2021). "Given that fasting activates GSK3β and AMPK, and SIRT7 silencing significantly attenuated the anti-tumor effect of fasting, we next examined the potential for manipulation of the GSK3β–SIRT7 axis to mimic the fasting effect." (PMID 34433808, 2021). "The tumor burden was generally much greater in PyMT;Sirt7+/− mice as shown by the greater tumor weight." (PMID 34433808, 2021). "This is consistent with our finding that GSK3β acts as a tumor suppressor, especially in the earlier stage of tumorigenesis, by stabilizing SIRT7 to suppress AKT activation." (PMID 34433808, 2021). "Our results showed that expression of CPT1A or SIRT5 was negatively correlated with deeper tumor infiltration and distant metastasis, whereas the expression of SIRT7 exhibited opposite effect." (PMID 33681201, 2021). "Taken together, these data indicated that SIRT7 functions as a tumor suppressor, suggesting the potential anti-tumor benefits of boosting SIRT7 expression." (PMID 34433808, 2021). "We next investigated the ability of Sirt7 overexpression to suppress tumor growth in Sirt7-TG mice, in which ectopic Sirt7 expression was induced by oral administration of doxycycline (DOX, 2 g/l in water)." (PMID 34433808, 2021). "By downregulating Sirtuin7(SIRT7) via sponging miR‐3666, circPVT1 can promote tumor growth and inhibit cell apoptosis in HCC." (PMID 33793089, 2021). "Specifically, ELK4 has been shown to recruit and stabilize epigenetic regulator SIRT7 to promote tumor growth and maintain rapid cellular proliferation." (PMID 32351540, 2020). "We injected both wild type- and SIRT7-depleted 22Rv1 cells into nude mice and measured the tumor volume and growth after 4 weeks." (PMID 32019578, 2020). "This further confirmed that the expression of SIRT7 in tumor tissues was significantly higher than that in normal tissues." (PMID 32528869, 2020). "SIRT7 causes carcinogenic effects by deacetylating H3K18; this weakens the transcription of target genes linked to tumor suppression." (PMID 33274232, 2020). "We examined the difference in SIRT7 expression between tumor and adjacent normal tissues by using RNA-seq data from multiple malignancies in TCGA." (PMID 32528869, 2020).
tumor (continued). "They found that elevated SIRT7 levels enhance tumor aggressiveness by promoting epithelial-to-mesenchymal transition (EMT)." (PMID 32019578, 2020). "The expression levels of SIRT1, SIRT3, SIRT5, SIRT6, and SIRT7 were significantly correlated with tumor stage and histological grade." (PMID 32158696, 2020). "Tumor weight and volume in animals administered SIRT7-depleted 22Rv1 cells increased significantly but more slowly (P = 0.0001 and P = 0.0003, respectively) than those in mice injected with normal 22Rv1 cells." (PMID 32019578, 2020). "We investigated the relationship between SIRT7 expression and tumor-infiltrating of immune cells (M1 macrophages and T cell exhaustion) based on the expression level of immune marker genes in the TIMER databases." (PMID 32528869, 2020). "These discrepant results regarding the effect of SIRT7 on oncogenesis are attributed to potential tumor-specific discrepancy." (PMID 32019578, 2020). "As the deacetylase activity of SIRT7 on H3K18Ac is necessary for the maintenance of the fundamental properties of tumor cells, the inhibition of SIRT7 by MYBBP1A suggests that MYBBP1A functions as a tumor suppressor." (PMID 31968688, 2020). "SIRT7 regulates fundamental cellular programs that participate in oncogenic transformation and tumor biology." (PMID 31121824, 2019). "SIRT7 was overexpressed in OC tissues and cell lines, omental metastasis tissues, and promoted tumor cell proliferative potential via regulating apoptosis." (PMID 31572453, 2019). "SIRT7 knock-down determines a reduction in tumor invasiveness and progression, and an induction of apoptotic pathways." (PMID 30761005, 2019). "SIRT7 is a biomarker for aggressive and metastatic tumors with poor clinical outcome, and its overexpression correlates with advanced tumor stage." (PMID 30761005, 2019). "In contrast with other studies, this report provides evidence of a new role for SIRT7 in tumor metastasis." (PMID 30761005, 2019). "Similar to the other sirtuins, SIRT7 has also been recognized as a tumor suppressor based on its negative regulation of HIF1 and HIF2 transcription, as previously discussed." (PMID 30510540, 2018). "SIRT7 as a tumor suppressor plays an important role in suppressing the epithelial-to-mesenchymal transition in oral squamous cell carcinoma." (PMID 30627559, 2018). "Of note, knocking down SIRT7 in 4T1 cells had little effect on cell growth in vitro, but it promoted in vivo primary tumor growth 21 days after inoculation, a later stage of tumor with nutrient limitation." (PMID 28827661, 2017). "We then evaluated the expression of known targets of miR-125a and found that sirtuin-7, matrix metalloproteinase-11, and c-Raf were up-regulated in tumor tissue by 2.2-, 3-, and 1.7-fold, respectively." (PMID 28445974, 2017). "Our immunohistochemical analysis of matched tumor and normal prostate tissue on 57 patients clearly demonstrated that the level of SIRT7 is increased in tumor." (PMID 29100388, 2017). "While the tumor growth and palpable tumor latency were merely affected, induced expression of Sirt7 remarkably inhibited lung metastasis." (PMID 28827661, 2017). "Based on these data collected in vitro, we measured the expression level of MMP11, Zbtb7a, SIRT7 and c-Raf in tumor biopsies, focusing on those patients showing a downregulation of miR-125a of at least 2-fold." (PMID 28445974, 2017).